MAP2K1 (mitogen-activated protein kinase kinase 1)
Diseases named in the same sentence as MAP2K1 in open-access papers (continued):
Sharing a sentence is not in itself a finding about the gene and the disease.
melanoma (continued). "Some studies have also shown that targeting MAP2K1 and MAP2K2, and MAP3K5 and MAP3K9 with specific drugs can be effective at inhibiting the growth of melanoma cells in preclinical models." (PMID 37504268, 2023). "In melanoma, multiple mechanisms of resistance to BRAF and MAP2K1/2 inhibition, including MAPK1/3 reactivation and PI3K-AKT1 pathway activation, converge upon MYC as a key element." (PMID 34831420, 2021). "Since that initial discovery, targeted therapies have been developed for the treatment of melanoma, such as BRAF and MAP2K1/2 inhibitor drugs." (PMID 34831420, 2021). "In fact, the inhibitory drugs of MAP2K1/2, more commonly called MEK inhibitors were identified to be effective in the treatment of melanomas." (PMID 35069558, 2021). "In-frame deletions in MAP2K1, previously shown in experimental models to be strongly MAPK-activating, characterized a significant subset of triple wild-type melanoma (2.0%), suggesting a primary oncogenic role for these mutations." (PMID 32483240, 2020). "In melanoma tumor cell lines, we did not detect any other mutation apart from the expected BRAF V600E, MAP2K1 P124S (_f1), and NRAS Q61K mutations (Dataset EV 3)." (PMID 38898234, 2024). "To date, there are no reports on effective small molecule inhibitors targeting MAP2K1/2 in melanoma." (PMID 35069558, 2021). "To determine whether the use of our system can be extended to the analysis of multiple loci, we designed a sgRNA library for three genes (MAP2K1, KRAS, and NRAS) related to vemurafenib resistance in melanoma." (PMID 32242071, 2020). "Among 253 melanomas, 129 (51.0%) BRAF, 45 (17.8%) NRAS, 6 (2.4%) KIT, 4 (1.6%) GNAQ, 2 (0.8%) GNA11, 2 (0.8%) MAP2K1 and no MAP2K2 gene mutations were detected by the biochip assay." (PMID 28881731, 2017). "Despite the absence of additional MAPK mutations, melanomas with Class II and III MAP2K1 mutations progressed to metastasis in one-eighth and one-third of cases, respectively, with the presence of TERT-p mutations being an independent predictor for metastatic disease." (PMID 40107205, 2025).
breast carcinoma (115 papers, 2006 to 2025). "The breast cancer stem cell phenotype is influenced by the repression of copper-dependent MAP2K1/MEK1 activity caused by HIF1-induced GSH." (PMID 39408933, 2024). "MEK1 protein kinase appears to be essential for normal development before birth and for survival after birth, but MAP2K1 mutations were observed in many human epithelial cancers, including esophageal cancer, gastric cancer, breast cancer, and CRC." (PMID 36746394, 2023). "This study provides a totally new and scientific way to holistically decipher that the pharmacological mechanisms of Damnacanthus indicus C.F.Gaertn in the treatment of breast cancer might be associated with MAP2K1, PIK3CA, and Raf1 genes." (PMID 30906409, 2019). "As an example of genes with MR and colocalization evidence on two cancer sites, MAP2K1 in cell type TN at resting (0 h) showed colocalization evidence on prostate cancer and breast cancer (colocalization probability PP.H4 = 94% and 93% respectively)." (PMID 41216857, 2025). "Hundred percent of the mutations found in breast cancer were located in ERBB2 and similarly, BRAF accounts for all mutations in colorectal cancer and MAP2K1 in pancreatic cancers." (PMID 32757330, 2020). "Output analysis showed that, in the breast cancer patients, MAP2K1 and PIK3CA have a significant relationship with the occurrence and prognosis of the breast cancer." (PMID 30906409, 2019). "The Rap1 signaling pathway is the main target of the Damnacanthus indicus C.F.Gaertn, and we found three overlapping genes (MAP2K1, PIK3CA, and Raf1) in the Rap1 signaling pathway associated with the breast cancer." (PMID 30906409, 2019). "From its initial discovery as the second Map2k1 kinase to defining the role of Map3k1 signal transduction in tumorigenesis and breast cancer, the road to understanding the intricate mechanisms of Map3k1 signaling has seemed to go on forever." (PMID 25613373, 2015). "Additionally, we discovered trans correlations between specific gene alterations (FANCA, HRAS, PIK3CA, MAP2K1, JAK2) and the expression of 22 proteins, suggesting potential molecular mechanisms underlying breast cancer development and progression." (PMID 39844043, 2025). "Furthermore, breast cancer patients with high expression levels of the ATF6α-MAP2K1/2-DDIT3 axis also showed decreased OS rates." (PMID 39466820, 2024). "The triple interaction of TPH2 rs1386483 and rs1473473 as well as RAF1 rs3729931 increased breast-cancer risk by 20%, a dual interaction of MAPK8 rs10857561 and MAP2K1 rs1347069 by 15%, and MAPK8 rs10857561 alone by 11% (all observed at a prior probability of 0.01)." (PMID 37789226, 2023). "NF1 loss-of-function mutations, RTKs mutations such as ERBB2 activating mutations, as well as alterations in other MAPK pathway genes (EGFR, KRAS, BRAF, and MAP2K1) were found to be enriched in endocrine-resistant advanced ER+ breast cancer compared to early-stage ER+ breast cancer." (PMID 38003387, 2023). "Selumetinib, another potential candidate targeting MAP2K1 and MAP2K2, has demonstrated efficacy in suppressing cell proliferation and migration in various cancers, including HER2-positive breast cancer." (PMID 40004024, 2025). "MAP2K1 expression was strongly correlated with expressions of EGFR (r= 0.252–0.62) in liver, lung, kidney, colon, head and neck, and breast cancers but negatively correlated in glioblastoma (r = −0.062)." (PMID 33842373, 2021). "Among the most significant overlaps we found up-regulated gene sets in MCF-7 breast cancer-, and MCF-10 mammary epithelium cell lines, where CCND1, MAP2K1 or EIF4G genes were over-expressed/knockdown, respectively." (PMID 31191821, 2019). "The MAP2K1, PIK3CA, and RAF1 and especially Raf1 are all believed to be the common suppressors in the breast cancer." (PMID 30906409, 2019).
breast carcinoma (continued). "Cu is required for binding to the dual specificity mitogen-activated protein kinase kinase 1 MEK1 and promotion of mitogen-activated protein kinase MAPK signaling and tumorigenesis by v-raf murine sarcoma viral oncogene homolog B BRAF in mammary tumors." (PMID 26583055, 2015). "Although functional studies have not directly implicated MAP2K1, POLR2J, and SEH1L in breast cancer development and progression, they have been associated with other malignancies." (PMID 38418940, 2024). "In particular, and in accordance with the interactions presented in this work, RAF1 targeting by miR-497 inhibits breast cancer cell growth, whereas downregulation of miR-424 leads to aberrant cell proliferation through MEK1 (MAP2K1) upregulation in senile hemangioma." (PMID 31976858, 2020).
lung cancer (76 papers, 2007 to 2025). A malignant neoplasm involving the lung. "Among the KRAS-wild type lung cancer cell lines analyzed, trametinib only impaired the viability of the H1437, a cell line that harbors MAP2K1 mutation." (PMID 38643157, 2024). "We detected 23 (23/30 = 76.7%) MAP2K1 mutations in lung cancer patients and four (4/30 = 13.3%) in colorectal cancer patients." (PMID 32757330, 2020). "MAP2K1 is rarely mutated in lung cancers (~1–2%) and implicated as an oncogenic driver in a small subset of LUAD that might benefit from MEK1 inhibitor therapy." (PMID 35641658, 2022). "In contrast to ERBB2, most of MAP2K1 mutations found in lung cancer are β3‐αC deletions." (PMID 32757330, 2020). "MAP2K1 mutation has been identified among subsets of smoking-associated lung carcinomas (mutually exclusive from EGFR, BRAF, KRAS, and NRAS mutations), lung adenocarcinoma in situ and early invasive disease, and KRAS/NRAS/BRAF/PIK3CA wild-type (“quadruple-wild-type”) colorectal carcinomas." (PMID 32483240, 2020). "Similar to lung cancer, MAP2K1 mutations are observed in about 1% of HNSCC cases." (PMID 31827134, 2019). "MAP2K1 variations influence signal transduction, cell proliferation, and metastasis, impacting lung cancer progression and treatment." (PMID 40136480, 2025). "Our analysis of lung cancer context-specific interaction networks of hub genes revealed that deregulated expressions of EGFR/MAP2K1/mTOR/TEAD1/YAP1 in lung cancer mediated abnormal expressions of 151 genes in total in 154 cancer-mediated interactions." (PMID 35655775, 2022). "Furthermore, we found that expression levels of these genes were associated with tumor metastasis; MAP2K1, mTOR, and TEAD1 were significantly overexpressed, while YAP and EGFR were under-expressed in metastasized lung cancer compared to primary tumors." (PMID 35655775, 2022). "Of these mutations, 97.8% (1583/1616) were found in lung cancer, with 96.71% (1530/1583) of the mutations in lung cancer were located in EGFR, 1.1% (17/1583) located in ERBB2, 0.7% (12/1583) located in BRAF, and 1.4% (23/1583) in MAP2K1." (PMID 32757330, 2020). "Finally, we included 10 well-known cancer-related genes (or their hotspot-containing exons) listed as most frequently mutated in lung cancer (BRAF,EGFR,ERBB2,HRAS,KRAS,MAP2K1,MET,NF1,NRAS, and RIT1) in the panel to serve as internal controls for highly mutated regions." (PMID 40867048, 2025). "This study proved for the first time that the exosomes secreted by lung cancer cell line H1299 could significantly change the expression of apoptosis related proteins MAP2K1, TUBA1C, RELA, and CASP6, thus promoting apoptosis of human astrocyte line SVG P12 cells." (PMID 36859173, 2023). "The average protein abundances among representative lung cancer proteins, EGFR, CDK1, and MAP2K1, revealed good linearity between the measured protein abundance and increasing cell numbers." (PMID 35013269, 2022). "Analysis of human lung cancer data sets derived from The Cancer Genome Atlas (TCGA) showed that KRAS, RAF1, MAP2K1, MAP2K2, MAPK3, and MAPK1 expression levels were positively correlated with the BCL6 expression level." (PMID 36377663, 2022). "Genetic alterations of EGFR, MAP2K1, mTOR, TEAD1, and YAP1 in The Cancer Genome Atlas (TCGA) cohorts of lung cancer occurred at respective frequencies of 15.0%, 1.80%, 6.00%, 1.80%, and 2.50%." (PMID 35655775, 2022). "Among the targets, MAPK1 and MAP2K1, two crucial proteins in MAPK signaling pathways, were further studied based on the fact that MAPK pathways were confirmed to be involved in MDR in lung cancer." (PMID 29137407, 2017).
lung cancer (continued). "Meanwhile, the MAP2K1 and MAP2K2 genes regulate cell proliferation and survival through the MAPK signaling pathway, and their abnormal activation drives tumor growth, metastasis, and drug resistance in lung cancer, making them critical therapeutic targets." (PMID 40136480, 2025). "Additionally, genes involved in the MAPK signaling pathway include BRAF, c-Jun, ERK, JNK, MAP2K1, MAP2K4, MAPK14, and KRAS, which are genes affected by MPs in lung cancer cells." (PMID 41378310, 2025). "Interestingly, we found that lung cancer cohorts with genetic alterations of EGFR, MAP2K1, mTOR, TEAD1, and YAP1 exhibited worse prognoses of overall, disease-specific, and progression-free survival compared to patients with wild-type (WT) genes." (PMID 35655775, 2022). "For instance, the overexpression of miR-449a directly inhibited the translation of mitogen-activated protein (MAP) kinase kinase MAP 2 K1, which decreased the activity of MEK1/ERK1/2/c-Jun pathway and suppressed the invasion and metastasis of lung cancer cells." (PMID 33593435, 2021). "DNA was also subjected to NGS using the Colon and Lung Cancer Research panel, which allows the assessment of the mutational status of additional genes including DDR2, MAP2K1 and FBX7, which are not covered by the Cancer Hotspot panel." (PMID 26068980, 2015). "Interestingly, we found that high expression levels of EGFR/MAP2K1/mTOR/TEAD1/YAP1 in lung cancer significantly decreased overall levels of active cytotoxic lymphocytes, mediated dysfunctional T-cell phenotypes, and produced worse overall survival rates of lung cancer cohorts." (PMID 35655775, 2022).
colorectal cancer (73 papers, 2008 to 2025). A primary or metastatic malignant neoplasm that affects the colon or rectum. "Mutations in MAP2K1 have been linked to poor prognosis in several cancers, including non-small cell lung, papillary thyroid, and colorectal cancers." (PMID 38992592, 2024). "Recently, two studies of plasma DNA sequencing in colorectal cancer patients undergoing treatment with EGFR monoclonal antibodies jointly identified the first MAP2K1 codon K57 resistance mutations (p.K57T and p.K57N)." (PMID 28179366, 2017). "MAP2K1 mutations in papillary thyroid cancer and colorectal cancer cases." (PMID 34046359, 2021). "Furthermore, a combination of Vectibix (panitumumab) and Mekinist (trametinib) caused tumor regression in a colorectal cancer patient harboring MAP2K1 (K57T)." (PMID 34504655, 2021). "We therefore sequenced these MAP2K1 loci (together with additional mutation hotspots in 34 other genes) in a series of plasma DNA samples collected from 22 colorectal cancer patients who acquired resistance to treatment with EGFR therapies (either Cetuximab or Panitumumab) after an initial response." (PMID 28179366, 2017). "For example, a 3-mm TA harbored one of the highest MB of 6.45, with pathogenic mutational defects in numerous colorectal cancer driver genes (e.g., APC, SOX9, TCF7L2, ASXL1, ERBB3, MAP2K1, and PTPRS)." (PMID 40757636, 2025). "In BRAFV600E-mutated colorectal cancers, CEMIP expression is increased in a β-catenin-dependent manner, which contributes to acquired resistance to Mitogen-activated protein kinase kinase 1 (MEK1) inhibition." (PMID 36291875, 2022). "Despite the major role of MAPK pathway in colorectal cancer (CRC) and papillary thyroid cancer (PTC), there are few reports about the prevalence of MAP2K1 mutations in these tumor sites." (PMID 34046359, 2021). "The region of gain of chromosome 1p included the colorectal cancer-associated genes REG4 and NOTCH2 and gain of 15q included the genes MAP2K1, SMAD3, SMAD6, and IGF1R, among others." (PMID 31620944, 2019). "While colorectal cancer cell lines have been frequently observed to display synergistic response to combined inhibition of MAP2K1/2 (MEK1/2) and PI3K27–30, weaker synergy has previously been observed in SW-620 and COLO 205 cells." (PMID 31664030, 2019). "Clinico-pathological characteristics of MAP2K1 mutant colorectal cancer cases." (PMID 34046359, 2021). "In advanced colorectal cancer, all the patients with MAP2K1 mutation treated with anti-EGFR, anti-EGFR combined with MEK and BRAF inhibitors, or anti-EGFR combined with ERK inhibitors, showed disease progression, where the MAP2K1 mutation was associated with poor response to targeted therapy." (PMID 35186740, 2022). "It promotes colorectal cancer progression by enhancing the interaction between BRAF and Mitogen-activated protein kinase kinase 1 (MEK1), leading to the activation of the mitogen-activated protein kinase (MAPK) signaling pathway." (PMID 40746885, 2025). "For example, in the monitoring of advanced colorectal cancer, ctDNA enables the dynamic and repeated assessment of changes in multiple key molecules of the tumor, such as EGFR, ERBB2, PIK3CA, and MAP2K1, among others." (PMID 39184861, 2024).
pancreatic cancer (49 papers, 2011 to 2025). "In colorectal and pancreatic cancers, additional co-mutations in KRAS (non-G12C alleles), EGFR, PIK3CA, BRAF, and MAP2K1 are frequently detected at baseline and are linked to primary resistance, underscoring the importance of comprehensive NGS at diagnosis." (PMID 40940900, 2025). "Patients with KRAS wild‐type disease and early‐onset pancreatic cancer (EOPC) harbored actionable mutations including BRAF, EGFR, ERBB2, and MAP2K1/2." (PMID 36999792, 2023). "Patients with KRAS wild‐type disease and early‐onset pancreatic cancer (EOPC) harbored actionable mutations including BRAF, EGFR, ERBB2, and MAP2K1/2.PGVs in PALB2, BRCA2, and ATM were associated with high PDAC risk in the Chinese population." (PMID 36999792, 2023). "Importantly, four of eight patients with follow-up data were diagnosed in early adulthood with rare forms of malignancies—schwannomatosis (LZTR1 and MAP2K1), pancreatic cancer (SOS2), and seminoma and germ cell neoplasia in situ (SOS1)." (PMID 38654924, 2024). "In pancreatic cancer cell lines bearing Kras mutation, the interaction between KLF11 and SMAD3 is inhibited, and treatment with ERK pathway inhibitors such as U0126 (highly selective inhibitor of mitogen-activated protein kinase kinase 1/2–MEK1/2) can revert the Kras effect." (PMID 37239940, 2023). "When similar analyses were performed with breast, colonic, and pancreatic carcinoma lineages, the SRPK1 knockdown impacted the expression of MAP2K2 instead of MAP2K1, providing additional evidence for this different response according to each cell line." (PMID 26244849, 2015). "Inhibition of mitogen-activated protein kinase kinase 1/2 (MEK1/2) inhibition also led to activation of the liver kinase B1/adenosine monophosphate (AMP)-activated protein kinase/Unc-51-like kinase 1 signaling axis, a key regulator of autophagy, in pancreatic cancer cells." (PMID 38892460, 2024).
gastric cancer (41 papers, 2015 to 2025). A primary or metastatic malignant neoplasm involving the stomach. "This study was important to evidence the RAS/MAPK activation driven by MAP2K1 depletion in gastric cancer." (PMID 36360266, 2022). "This pioneering study evaluated the knockdown effect of dual-specificity mitogen-activated protein kinase 1 (MAP2K1) and the relationship of MEK-inhibitory drugs with cancer cell lines, including gastric cancer." (PMID 36360266, 2022).
glioma (36 papers, 2007 to 2025). A benign or malignant brain and spinal cord tumor that arises from glial cells (astrocytes, oligodendrocytes, ependymal cells). "The alterations of CDKN2B, KMT5B, MAP2K1, PIK3CA, and chr9p were associated with hemorrhage, and this may be due to the fact that most of them affect glioma cell proliferation and invasion." (PMID 38877400, 2024). "Since miR-181b-abundant glioma cells is more sensitive to temozolomide (TMZ), aplysin enhances TMZ action through increasing the expression of miR-181 in TMZ-resistant glioma cells, which results in MEK1 (mitogen-activated protein kinase kinase 1) downregulation." (PMID 28052018, 2017).
colon carcinoma (34 papers, 2008 to 2025). "Although MAP2K1 mutations were more frequent in right-sided tumors, they were also detected in left colon tumors." (PMID 31226844, 2019). "Clonal mutations of MAP2K1 are associated with a worse prognosis in colon cancer patients." (PMID 35962343, 2022). "Overlapping analysis revealed that only GSK3α and MAP2K1 could predict the prognosis of colon cancer patients in stages II-IV." (PMID 37031867, 2023). "In addition, BMS-754807 treatment induced phosphorylation of mitogen-activated protein kinase kinase 1 and 2 (MEK1/2), which contributed to BMS-754807-induced p70S6K1 activation for survival in colon cancer cells." (PMID 32843616, 2020).